SERPINC1 (serpin family C member 1)
Description:
Most important serine protease inhibitor in plasma that regulates the blood coagulation cascade. AT-III inhibits thrombin, matriptase-3/TMPRSS7, as well as factors IXa, Xa and XIa. Its inhibitory activity is greatly enhanced in the presence of heparin.
Synonyms: ATIII; AT3; MGC22579; AT3D; ATIII-R2; ATIII-T1; ATIII-T2; THPH7
Tractability: Small molecule: a structure with a bound ligand is known; it has a high-quality binding pocket; it belongs to a druggable protein family. Antibody: its Gene Ontology location is reachable by antibodies, with high confidence; UniProt places it where antibodies can reach, with medium confidence; UniProt predicts a signal peptide or a membrane-spanning region. PROTAC: a small molecule that binds it is known. Other modalities: an approved drug acts on it.
Target class: Secreted protein
Safety:
Unwanted effects reported when the protein is acted on. In parentheses: how it was acted on, where the effect was seen, and who reports it.
thrombocytopenia (source: ClinPGx)
Gene: Protein-coding gene on chromosome 1 (173,903,519 to 173,917,543, reverse strand). Ensembl gene ENSG00000117601.
Subcellular location: Secreted, extracellular space
Pathways (Reactome):
Hemostasis: Amplification and propagation of coagulation cascade; Fibrin formation; Initiation of coagulation cascade; Regulation of clotting cascade
Metabolism of proteins: Post-translational protein phosphorylation; Regulation of Insulin-like Growth Factor (IGF) transport and uptake by Insulin-like Growth Factor Binding Proteins (IGFBPs)
Gene Ontology:
Molecular function: identical protein binding; protease binding; protein binding; serine-type endopeptidase inhibitor activity
Biological process: blood coagulation; regulation of blood coagulation
Cellular component: blood microparticle; extracellular exosome; extracellular matrix; extracellular region; endoplasmic reticulum lumen; plasma membrane
Genetic constraint (gnomAD): Loss-of-function variants: 12 observed, 44.14 expected, observed/expected ratio (o/e) 0.27, 90% interval 0.17 to 0.44. The upper end of that interval is the gene's LOEUF score, 0.44, which puts it in group 1 of 6, group 1 being the genes least tolerant of losing a copy. Missense variants: 421 observed, 607.96 expected, observed/expected ratio (o/e) 0.69, 90% interval 0.64 to 0.75. Synonymous variants: 210 observed, 231.78 expected, observed/expected ratio (o/e) 0.91, 90% interval 0.81 to 1.02.
Gene-disease validity (ClinGen):
ClinGen rates the evidence that SERPINC1 causes each of these diseases.
hereditary antithrombin deficiency (semidominant): Definitive. A rare, genetic, hematological disease characterized by decreased levels of antithrombin activity in plasma resulting in impaired inactivation of thrombin and factor Xa.
Homologues: Orthologues: chimpanzee SERPINC1 (99% identical), macaque SERPINC1 (97% identical), pig SERPINC1 (89% identical), dog SERPINC1 (88% identical), mouse Serpinc1 (88% identical), rabbit SERPINC1 (85% identical), tropical clawed frog serpinc1 (66% identical), rat Serpinc1 (57% identical), zebrafish serpinc1 (56% identical). Paralogues in human: SERPINB3 (32% identical), SERPINB4 (32% identical), SERPINB1 (32% identical), SERPINB9 (31% identical), SERPINB11 (31% identical), SERPINB8 (31% identical), SERPINB6 (30% identical), SERPINB12 (30% identical), SERPINB13 (29% identical), SERPINB2 (28% identical), SERPINB10 (28% identical), SERPINI2 (28% identical), and 24 more.
Diseases named in the same sentence as SERPINC1 in open-access papers:
SERPINC1 is named in the same sentence as 292 diseases in open-access papers, as found by Europe PMC text mining. Sharing a sentence is not in itself a finding about the gene and the disease. The quoted sentences say what the papers report.
thrombophilia (119 papers, 2001 to 2026). A condition characterized by an abnormally high level of thrombi. "BACKGROUND: Inherited antithrombin deficiency (ATD), a rare autosomal dominant disorder due to SERPINC1 gene mutations, is the most severe inherited thrombophilia." (PMID 41888834, 2026). "This study aimed to characterize SERPINC1 gene mutations in a Chinese cohort and to explore their relationship with thrombophilia." (PMID 41888834, 2026). "Frequent thrombophilia-related variants occurred in F5, SERPINC1, MTHFR, and FII, and inherited thrombocytopenias were linked to MPL, ANKRD26, THPO, DIAPH1, and ADAMTS13." (PMID 41929524, 2026). "Subsequent targeted genetic testing revealed a heterozygous SERPINC1 nonsense variant classified as likely pathogenic for antithrombin deficiency, suggesting underlying hereditary thrombophilia." (PMID 41602335, 2026). "Hereditary AT deficiency, a common autosomal dominant genetic disorder caused by mutations in the SERPINC1 gene, is recognized as the most severe form of inherited thrombophilia." (PMID 39707449, 2024). "Our findings shed light on the molecular pathogenesis of thrombophilia associated with disease-causing variations in SERPINC1." (PMID 39707449, 2024). "Five SERPINC1 mutations causing antithrombin deficiency, the strongest congenital thrombophilia were selected from a cohort of 350 unrelated patients based on functional, biochemical, and crystallographic evidence supporting a folding defect." (PMID 38968282, 2024). "In this regard, the utility of the SERPINC1 gene test in ischemic stroke remains elusive, even though hypercoagulability is one of the risk factors for arterial thrombosis." (PMID 35720094, 2022). "The findings support the association between c.391C > T in SERPINC1, thrombophilia, and atresia of the IVC system and indicate that even heterozygosity for c.391C > T may contribute to such anomalies." (PMID 39129027, 2024). "Furthermore, two patients had inferior vena cava (IVC) atresia, the manifestation of AT deficiency that has recently been reported in very severe thrombophilia patients with SERPINC1 p.Leu131Phe, Budapest 3, homozygotes." (PMID 35720094, 2022). "Atresia of the infrarenal inferior vena cava (IVC) is associated with thrombophilia and antithrombin (AT) deficiency (ATD) due to homozygosity for the so-called Budapest 3 variant, c.391C > T, in the gene, SERPINC1." (PMID 39129027, 2024). "Multiplex ligation-dependent probe amplification (MLPA) identifies genetic structural variants in SERPINC1 in 5% of cases with antithrombin deficiency (ATD), the most severe congenital thrombophilia." (PMID 36902454, 2023). "A 50-year-old Caucasian woman who took gestodene 75 μg/ethinylestradiol 20 μg as oral contraceptive, was sent to our thrombophilia clinic because, on thrombophilia testing, a reduction of SERPINC1 (74%) and a slight increase in circulating D-dimer and homocysteine were found." (PMID 37501065, 2023). "Inherited thrombophilia (e.g., venous thromboembolism, VTE) is due to rare loss-of-function mutations in anticoagulant factors genes (i.e., SERPINC1, PROC, PROS1), common gain-of-function mutations in procoagulant factors genes (i.e., F5, F2), and acquired risk conditions." (PMID 34207366, 2021). "In addition, SERPINC1 and F5 genes map closely in the same region of chromosome 1 and this might allow the combined defect to co-segregate in cis exacerbating severity and penetrance of inherited thrombophilia." (PMID 34207366, 2021).
Sepsis (66 papers, 2006 to 2026). Sepsis is defined as life-threatening organ dysfunction caused by a dysregulated host response to infection. "Antithrombin III (SERPINC1) as well as Alpha-2-antiplasmin (SERPINF2) are both important regulators of the coagulation cascade and were reported to be associated with sepsis mortality and organ dysfunction." (PMID 40898225, 2025).
thrombosis (64 papers, 2001 to 2026). "Congenital antithrombin deficiency is an autosomal dominant disease that results in deep venous thrombosis and pulmonary embolism, which is mainly caused by mutations in the antithrombin gene (SERPINC1)." (PMID 38093370, 2023). "Hereditary AT deficiency is a rare autosomal dominant thrombotic disease mainly caused by mutations in SERPINC1, which was usually manifested as venous thrombosis and pulmonary embolism." (PMID 36624481, 2023). "rs2227589, a polymorphism of SERPINC1 gene (NG_012462.1:g.5301G > A), was found to be associated with the risk of venous thrombosis in a Dutch population." (PMID 31572449, 2019). "The homozygous variant (Phe229Leu) of SERPINC1 leading to spontaneous antithrombin polymerization in vivo has been shown to be associated with severe childhood thrombosis." (PMID 31572449, 2019). "Background and Aims: Genetic variants in the gene SERPINC1 have been shown to be associated with antithrombin deficiency, which subsequently contributes to the susceptibility to venous thrombosis." (PMID 31572449, 2019). "Genetic variations in coagulation system genes (such as F5, PROC, and SERPINC1) contribute to susceptibility to venous thrombosis." (PMID 31572449, 2019). "A family with severe thrombosis and antithrombin deficiency, the strongest anticoagulant, carried a new mutation affecting the translation-start codon of SERPINC1, the gene encoding antithrombin." (PMID 30237862, 2018). "Sequencing of SERPINC1 in 4 relatives with antithrombin deficiency and relevant thrombotic history, including pulmonary embolism, stroke and recurrent thrombosis, confirmed the presence of the c.3G>T mutation in heterozygous state in all patients." (PMID 30237862, 2018). "Here, we report the identification of a recurrent hotspot in SERPINC1 that severely increases the risk of venous thrombosis in the Chinese population." (PMID 29137435, 2017). "Rare mutations in PROC, PROS1 or SERPINC1 as well as common variants in F5, F2, F11 and SERPINC1 have been identified as risk factors for deep vein thrombosis (DVT)." (PMID 26982741, 2016). "In this study, we hypothesized that arterial thrombosis associated with altered AT would have comparable detectability of pathogenic SERPINC1 variants with venous thrombosis." (PMID 35720094, 2022). "In China, genetic thrombophilia patients mainly suffer from deficiencies in AT III, protein S, and protein C. Multiple mutations in the serpin family C member 1 (SERPINC1) can affect AT III activity, resulting in thrombosis." (PMID 38457560, 2024). "Notably, individuals carrying combined mutations in the SERPINC1 and PROC genes have a significantly higher risk of venous thrombosis." (PMID 41839631, 2026). "Patients carrying nonsense mutations in SERPINC1, having a high risk of thrombosis, do not usually display the clinical severity shown by this family." (PMID 30237862, 2018). "Moreover, the SERPINC1 gene test was not performed for four symptomatic patients with AT deficiency, three ischemic stroke patients, and one venous thrombosis patient." (PMID 35720094, 2022). "In the present study, we performed whole-exome sequencing of a Chinese family with deep vein thrombosis, and identified a new small deletion that eliminates four amino acids (INEL) from exon 4 of SERPINC1 gene." (PMID 27708219, 2016). "The current evidence could not support clinicians in testing the AT and SERPINC1 genes in arterial thrombosis, contrary to venous thrombosis." (PMID 35720094, 2022).
antithrombin deficiency (33 papers, 2014 to 2026). "Over 300 genetic variants responsible for antithrombin deficiency have been discovered for the SERPINC1 gene." (PMID 40097149, 2026). "More than 386 different variants affecting SERPINC1, the gene encoding antithrombin, have been described as causative of antithrombin deficiency." (PMID 38968282, 2024). "Whole exome sequencing revealed a heterozygous missense variant of uncertain significance in the SERPINC1 gene, which has been associated with hereditary antithrombin deficiency." (PMID 39403403, 2024). "We performed whole exon sequencing on the patient and detected a novel heterozygous missense mutation in SERPINC1 gene (1q25.1) in the proband, which is related to antithrombin deficiency (ATD)." (PMID 38579030, 2024). "Functional antigenic and biochemical data of SERPINC1 mutations identified in patients with antithrombin deficiency and selected for predictions using AlphaFold." (PMID 38968282, 2024). "We report a pregnant case with novel mutation in SERPINC1 presenting transient antithrombin deficiency and multiple venous thromboembolisms." (PMID 38093370, 2023). "Our study enriched the mutation database of SERPINC1 gene, provided some new theoretical basis for gene diagnosis and genetic counseling of patients with transient antithrombin deficiency." (PMID 38093370, 2023). "Sixteen out of twenty four (66.7%) patients with antithrombin deficiency carrying the homozygous SERPINC1 p.Leu131Phe mutation (antithrombin Budapest 3) had IVC system atresia, possibly caused by thrombosis in the developing fetal vessels." (PMID 35627118, 2022). "Inherited antithrombin deficiency due to mutations in the SERPINC1 gene is the genetic basis of this patient, and warfarin/rivaroxaban, other than heparin, is beneficial." (PMID 36093136, 2022). "Analysis of antithrombin III deficiency patients with SERPINC1 gene test and pathogenic variant detection rate." (PMID 35720094, 2022). "Most VTE subjects with antithrombin deficiency have been found to carry genetic variants of SERPINC1." (PMID 31572449, 2019). "The present work has characterized a new SERPINC1 mutation identified in a family with antithrombin deficiency that displayed very severe clinical phenotype." (PMID 30237862, 2018). "Thrombophilic studies revealed a strong defect, antithrombin deficiency, which was explained by a new SERPINC1 mutation (c.651-653delCAT)." (PMID 28303970, 2017). "Demographic, clinical, analytical and genetic features of patients with antithrombin deficiency and mutations affecting potential regulatory sequences in SERPINC1." (PMID 27003919, 2016). "The study of a severe thrombophilic family with antithrombin deficiency has identified not only a new mutation in SERPINC1, but also new clues on potential new pathological functions of unexpected aberrant proteins and fascinating news on the initiation of translation." (PMID 30237862, 2018). "The mutation of the initiation methionine codon of SERPINC1 identified in a thrombophilic family could explain the apparent type I antithrombin deficiency diagnosed in carriers." (PMID 30237862, 2018). "Indeed, current functional methods to diagnose antithrombin deficiency fail to detect pathogenic mutations in SERPINC1, the gene encoding antithrombin, and certain mutations in SERPINC1 may only show pathogenicity under specific conditions." (PMID 29137435, 2017). "In SERPINC1, from the available data of the Human Gene Mutation Database (HGMD), 90.4% most of the defects causing antithrombin deficiency are SNVs and INDELs SERPINC1." (PMID 36902454, 2023). "Mutations in the serpin family C member 1 gene (SERPINC1) can lead to Quantitative (type I) and Qualitative (type II) types of antithrombin deficiency." (PMID 32252658, 2020). "Antithrombin deficiency (AT3D, #MIM613118), which is the result of variants of the inhibitory serpin antithrombin III (AT3, SERPINC1), leads to venous thromboembolic disease." (PMID 30633749, 2019).
antithrombin deficiency (continued). "The identification of antithrombin deficiency without SERPINC1 defects and hypoglycosylation was the first clue of a CDG." (PMID 32530140, 2020). "Congenital disorder of glycosylation diagnosis started through the identification of antithrombin deficiency without SERPINC1 defect and the detection of hypoglycosylated forms." (PMID 32530140, 2020). "We speculated that the analysis of those cases with antithrombin deficiency that had no genetic defects in exons and flanking regions of SERPINC1 might help to identify new mechanisms associated with deficiency of this key anticoagulant." (PMID 27003919, 2016). "MLPA detects all SVs affecting SERPINC1 exons regardless of their type (deletion or duplication), but this method does not detect SVs affecting introns of this gene, such as deletions, or retrotransposon insertions, despite the fact that these defects also cause antithrombin deficiency." (PMID 36902454, 2023). "Thus, variations located in the coding regions of SERPINC1 but not the rs2227589 (C > T) located in the intron may cause antithrombin deficiency." (PMID 31572449, 2019). "Accordingly to the in silico results, we decided to sequence 1500 bp of the 5' region, intron 1 and intron 2 of SERPINC1, regions containing the potential VDRE regions, in 23 patients with antithrombin deficiency without mutations in coding exons and flanking regions or gross gene defects." (PMID 27003919, 2016).
COVID-19 (28 papers, 2020 to 2025). A disease caused by infection with severe acute respiratory syndrome coronavirus 2. "However, new evidence points to its activity within the coagulation cascade, interfering with antithrombin/SERPINC1 and factor XIIa leading to increased coagulation indicating an increased tendency for procoagulant disorders in COVID-19 patients." (PMID 36967377, 2023). "In our results, F11, F9, FGG, FGA, SERPINA5, SERPINC1, and SERPINF2 are involved in the coagulation cascade, and significantly higher expressed in COVID-19-children compared with COVID-19-adults." (PMID 34335977, 2021). "Other proteins that could potentially be employed in therapies against COVID-19 but that so far have not been associated with the disease are CD5L, VDBP, A1BG, C4BPA, PGLYRP2, SERPINC1, and APOH." (PMID 37371071, 2023). "On the contrary, we found a number of plasma serine protease inhibitors such as SERPINA5, SERPINC1, and SERPINF2, which negatively regulate the blood coagulation cascade 29, were strongly up-regulated in COVID-19-children against in healthy children or COVID-19-adults." (PMID 34335977, 2021). "In addition, other proteins that could be employed in therapies against COVID-19 but that so far have not been associated with the disease are CD5L, VDBP, A1BG, C4BPA, PGLYRP2, SERPINC1, and APOH." (PMID 37371071, 2023).
Stroke (21 papers, 2005 to 2026). Sudden impairment of blood flow to a part of the brain due to occlusion or rupture of an artery to the brain. "In the “stroke” group, enriched genes implicated increased activity of the blood coagulation cascade and increased complement activation; Notable among these genes is SERPINC1 that encodes antithrombin." (PMID 32898326, 2020). "In the “stroke” group, significant genes implicated were associated with increased activity of the blood coagulation cascade and increased complement activation, for example, SERPINC1, which encodes antithrombin." (PMID 32898326, 2020). "Likewise, we suggest that mutation of the SERPINC1 gene could have close links with stroke, especially atypical stroke mechanisms and vascular traits." (PMID 35720094, 2022). "For the extreme contrast of “stroke” versus “long survivor”, only four gene sets – SERPINC1, SLC22A5, CACNA1H, and SLC4A1 [MIM: 109270] – were significant." (PMID 32898326, 2020). "Three genes (HGF, SNTB1, and SERPINC1 [MIM: 107300]) were found in the “stroke” group but not in the “long survivor” group." (PMID 32898326, 2020). "When the asymptomatic patients with SERPINC1 variant (n = 5), the symptomatic patients whose SERPINC1 gene was not tested (n = 4), and symptomatic patients whose SERPINC1 gene tested but AT activity was normal or not tested (n = 8), are included, the proportion of stroke is 27.8% (10/36)." (PMID 35720094, 2022).
Thromboembolism (16 papers, 2005 to 2025). The formation of a blood clot inside a blood vessel that subsequently travels through the blood stream from the site where it formed to another location in the body, generally leading to vascular occlusion at the distant site. "SERPINC1 congenital or acquired deficiencies represent a significant risk factor for thromboembolic disease." (PMID 37501065, 2023). "Even minor downregulation of SERPINC1 can increase the risk of thromboembolism." (PMID 34783290, 2021).